CD44 (CD44 molecule (IN blood group))
Diseases named in the same sentence as CD44 in open-access papers (continued):
Sharing a sentence is not in itself a finding about the gene and the disease.
pancreatic cancer (continued). "It has been reported that cells expressing cell surface markers CD44, CD24 and EPCAM in pancreatic tumors have the potential to promote the formation, proliferation and metastasis of cancer cells, and these cells were entitled as pancreatic cancer stem cell (CSC) by researchers." (PMID 35733218, 2022). "Therefore, simultaneous targeting of CD44 and MCT1 may be a judicious strategy for pancreatic cancer patients with recurrence after conventional chemotherapy such as gemcitabine treatment." (PMID 36302783, 2022). "al., who found that not only did CD44, a marker for PCSC, correlate with metastasis, recurrence and poor outcomes, but that an antibody directed against this surface protein was able to reduce the growth, metastasis and recurrence of human pancreatic tumor xenografts in mice." (PMID 34203589, 2021). "Indeed, we found that pancreatic cancer stem-like cells expressing CD24/CD44 were targeted by L-fucose liposomes (data not shown)." (PMID 27233074, 2016). "Only BAY 1170–82 pretreatment could effectively block OPN-mediated increase in LC3-II expression and the populations of LC3+/ALDH1+ cells and CD44+/CD133+ cells in PANC-1 cells, suggesting that OPN activated autophagy via NF-κB to increase pancreatic cancer stemness." (PMID 26458814, 2015). "We observed that the number of CD44+CD133+ cells was increased by the autophagy inducer rapamycin but was decreased by the autophagy inhibitor CQ or knockdown of autophagy-related genes, revealing the requirement of autophagy for the maintenance of CD44+CD133+ cells in pancreatic cancer." (PMID 26458814, 2015). "In pancreatic cancer, several markers have been used to identify CSCs, such as epithelial cell adhesion molecule (EpCAM, also known as epithelial-specific antigen, or ESA), CD24, CD44, CD133, CXCR4, aldehyde dehydrogenase 1 (ALDH1) and combinations of these markers." (PMID 25240521, 2014). "The same results were not achieved with CD44-/CD24- pancreatic cancer cells." (PMID 23419168, 2013). "We have recently demonstrated that pancreatic CSC's expressing stem cells markers CD133, CD44, CD24, ESA, express high levels of pluripotency maintaining factors, and drug resistance genes MDR1 and ABCG2 as compared to normal pancreatic cells and pancreatic cancer cells." (PMID 23029396, 2012). "The intriguing observation that both CD133 positive and CD44+/CD24+ cells have been found to be tumor initiating cells and possess many of the characteristics of cancer stem cells suggests that heterogeneity exists in the pancreatic cancer stem cell population." (PMID 22570653, 2012). "We next examined the expression of stem cell markers (CD133+CD44+CD24+ESA+), pluripotency maintaining factors (Nanog), signaling molecule (Notch-1) and drug resistant genes (MDR1 and ABCG2) in human normal pancreas, primary pancreatic cancer cells, and CSCs by q-RT-PCR." (PMID 21304978, 2011). "More importantly, our results demonstrate for the first time that the CD44+/CD133+ tumor-initiating cells, or pancreatic cancer stem cells, have a low level of miR-34 accompanied by a high level of Bcl-2, suggesting a potential link of miR-34 and its target Bcl-2 to pancreatic cancer stem cells." (PMID 19714243, 2009). "Importantly, in pancreatic cancer specifically, LY6E was suggested to be a marker for cancer cells with stem cell properties and was used in addition to the stem cell markers TACSTD1 and CD44 to establish a sorting technique to obtain clonal colony-forming pancreatic cancer stem cells." (PMID 33613843, 2021). "Interestingly, the PANC-1 CSC pancreatic cancer spheroids could be subcultured several times for at least seven generations, and these CSC pancreatic cancer spheres, again, contained only 2.8–7.5% of CD44+CD24+EpCAM+ cells after prolonged culture." (PMID 34885233, 2021).
pancreatic cancer (continued). "In addition, this study provides a comprehensive mechanism for ZIP4-mediated pancreatic cancer growth involving CREB-dependent transcription, enhancement of oncogenic miR-373 expression, and reduction in key miR-373 regulated targets, including the tumour suppressor genes TP53INP1, LATS2 and CD44." (PMID 23857777, 2013). "Notably, the existence of apparently ALDH negative, CD133 negative, or CD44 negative pancreatic tumors could have several explanations." (PMID 24213498, 2012). "As for pancreatic cancer HPC-Y5 cells, although the ratio of CD44+/CD24+ cells did not exhibit a significant change due to the small size of the double-positive cell subset, the subpopulation of CD44−/CD24− cells was increased following fisetin treatment." (PMID 37743465, 2023). "The addition of IL-17A to pancreatic cancer cells did not increase the subpopulation of cells expressing the typical stem cell markers such as CXCR4, ABCG2, and CD44." (PMID 32210079, 2020). "It has been shown that a ninefold increase in Sonic hedgehog mRNA levels were present in the CD44 and CD24 PDAC positive cells compared to the pancreatic cancer cells with low or absent expression of these biomarkers." (PMID 28659655, 2017). "We examined the effect of low concentrations of metformin on different subpopulations of pancreatic cancer cells and found that these selectively inhibited the proliferation of CD133+ but not CD24+CD44+ESA+ cells." (PMID 23667692, 2013). "Regarding the effects of OSM in mediating stemness and pluripotency, OSM was shown to induce a mesenchymal CD44 high/CD24 low phenotype in breast and pancreatic cancer cells, and this action was unique to OSM and not observed following IL-6 exposure in pancreatic cancer cells." (PMID 34361105, 2021). "However, while ongoing clinical trials are performed with several CD44 inhibitors (e.g., NCT02046928, NCT03078400), none is applied to pancreatic cancer patients." (PMID 33578795, 2021). "Unlike CD44 and CD133, ALDH1 showed a high correlation with LC3 expression in pancreatic tumors." (PMID 26458814, 2015). "Considering the small effect of low concentrations of metformin on the proliferation of pancreatic cancer cells in general, it can be inferred that the proliferation of CD133+ cells, but not CD24+, CD44+, ESA+, or CD24+CD44+ESA+ cells, was selectively inhibited." (PMID 23667692, 2013). "In addition, we found that GA could downregulate the expression of some stem cell-related genes in pancreatic cancer cells, such as ALDH and CD44 (data not shown)." (PMID 28797284, 2017). "Thus, in pancreatic cancer, the mouse strains used to date do not appear to affect the frequency of tumor initiation, further supporting the idea that CD24/CD44 cells in ALDHhigh and ALDHlow populations are unlikely to contribute to tumor initiation in our studies." (PMID 21695188, 2011).
lung carcinoma (262 papers, 2005 to 2026). "Increased expression of CD44 has been associated with the proliferation of human lung cancer cells and their resistance to treatment." (PMID 40670469, 2025). "Studies have shown that the upregulation of CD133 and CD44 in lung cancer cells is associated with the induction of EMT, which is a critical step in the development of metastasis." (PMID 38672078, 2024). "HA interacts with hyaluronan mediated motility receptor (RHAMM) and CD44, and the inhibition of either of these proteins causes lung cancer cells to switch to an epithelial phenotype." (PMID 38139154, 2023). "CD44 overexpression has been linked to drug resistance in lung cancer with CD44+ lung cancer cells being more resistant to cisplatin than CD44− cells." (PMID 36766747, 2023). "In a previous meta-analysis study, it was reported that CD44 was associated with the migration ability of lung cancer cells." (PMID 34439211, 2021). "High expression of CD44 mRNA in lung cancer tissues was associated with poor overall survival of patients." (PMID 34439211, 2021). "HA and CD44 are overexpressed in NHLFs/LCAFs (normal human lung fibroblasts vs. lung cancer-associated fibroblasts), followed by NSCLC cells." (PMID 34976811, 2021). "Using an online dataset, we found that CD44 overexpression is associated with poor survival of lung cancer patients." (PMID 34439211, 2021). "CD44 has been reported to be associated with a poor prognosis of lung cancer, where it has been established that lung cancer cell lines that are CD44+ had increased proliferative and colony-forming potential." (PMID 34527268, 2021). "We first evaluated the association between CD44 mRNA expression in lung cancer tissues and patient survival by using online microarray datasets." (PMID 34439211, 2021). "Using the AJCC TNM staging system for lung cancer, we observed that the CD44 rs713330 T/C polymorphism was highly associated with the “T” classification (AOR = 4.250, 95% CI = 1.529–11.814; p = 0.006) in male patients with lung adenocarcinoma." (PMID 32344833, 2020). "The chloroform fraction also inhibited the growth of the A549 spheroid by suppressing the spheroid size, inducing apoptosis, reducing the proportion of CD44 lung cancer stem cells, causing arrest at the S phase of the cell cycle, and suppressing the expression of the SOX2 and MYC genes." (PMID 37513848, 2023). "In addition, the overexpression of CD44 has been associated with poor prognosis and drug resistance in lung cancer." (PMID 35806135, 2022). "To further investigate the underlying mechanisms by which CD44 promotes lung cancer cell migration, we evaluated the protein expression of commonly involved pathways, including Akt, Jak/Stat, and ERK pathways, and found that ERK phosphorylation was upregulated in CD44-overexpressing cells." (PMID 34439211, 2021). "Notably, overexpression of several of these genes, such as CD151 and CD44, has been observed in lung cancer and is associated with poor prognosis." (PMID 34663427, 2021). "Additionally, Snail has been reported to regulate Nanog, inducing stemness properties in lung cancer and, along with integrin α6, Snail, and CD44, has been associated with cell migration, invasion, and metastasis." (PMID 31506430, 2019). "CD44+ H1650-CSCs and CD44+ lung cancer patient-derived organoids also showed increased CD146 expression after co-culture with astrocytes." (PMID 41356185, 2026). "CD44 is highly expressed in human lung cancers and plays critical roles in epithelial–mesenchymal transition, tumor invasion, and metastatic progression." (PMID 41551982, 2026). "The existence of the CD44+CD146+ BrM-CSC subpopulation was further confirmed in lung cancer brain metastatic tissue and patient-derived organoid samples." (PMID 41356185, 2026). "Free SN38 reduced CD44 protein expression, and Au/HA NP internalization significantly downregulated CD44 expression in lung cancer cell lines, confirming active CD44 engagement and NP endocytosis." (PMID 41551982, 2026).
lung carcinoma (continued). "The result showed varying levels of CD44 expression varied among the three lung cancer cell lines, with the expression being the highest in A549 cells, followed by that in H226 cells." (PMID 41551982, 2026). "Here we found that CD146+ pericyte-like tumor cells derived from CD44+ BrM-CSCs potently exert pro-angiogenic effects through dual effects on the VEGFA-VEGFR2 axis in lung cancer BrM." (PMID 41356185, 2026). "Collectively, those data indicated that CD44+ lung cancer BrM-CSCs mimic pericytes through the acquired overexpression of CD146." (PMID 41356185, 2026). "According to western blot and immunofluorescence analyses, SM-3-treated human lung cancer cells (A549, H292, and H460) showed decreased levels of stem cell markers (CD44, CD133, ALDH1 A1) and stem cell transcription factors (NANOG, OCT4, SOX2)." (PMID 40287470, 2025). "The key gene alterations associated with lung cancer recurrence include PD-L1 mutations that enable the tumor cell to evade immune surveillance, and CD8 and CD44 mutations that play roles in cell adhesion and migration." (PMID 40507370, 2025). "After entrance, it inhibits the expression of NF-kB, FAK, and MAPK genes, as well as the expression of the CD44 protein in lung cancer tissues, indicating its ability to inhibit lung cancer growth." (PMID 40670469, 2025). "CD44-targeted nanocarriers are emerging as flexible challengers in the field of cancer therapies, namely in the promising area of immunotherapy for lung cancer." (PMID 41367861, 2025). "These biomimetic nanocarriers, which mimic the lipid make-up and surface properties of the cell membrane of lung cancer, have been shown to have enhanced cellular affinity for CD44 cancer-overexpressing cells, leading to better uptake and immune activation." (PMID 41367861, 2025). "The A549 SC side population CD133+ and CD44+ isolated from the total lung cancer cells (A549) population via the magnetic bead separation technique were identified by immunofluorescence." (PMID 39957816, 2025). "This study was conducted in vitro using A549 cells (a human lung carcinoma cell line with high CD44 expression) and HepG2 cells (a liver cancer cell line with low CD44 expression)." (PMID 40277711, 2025). "CD44 is also recognized as a tumor-initiating marker in lung cancer cells, supported by both in vitro and in vivo studies." (PMID 40287470, 2025). "A study on lung cancer found primary tumors with higher CD44 expression increased metastasis to regional lymph nodes, and an enrichment of CD44 + cells in metastatic lymph nodes compared to primary tumors." (PMID 41013561, 2025). "The CD44-HA interaction has been found to promote immune evasion by inhibiting Fas expression during Fas/Fas ligand T cell-mediated cytotoxicity in lung cancer cells." (PMID 39333557, 2024). "It has been reported that the knockdown of PKM2 in CD44+ lung cancer stem-like cells by siRNA significantly reduces spheroid formation and increases their sensitivity to cisplatin and gamma-ray treatment." (PMID 38203787, 2024). "The tLyp-1-Lam2b-siSOX2 exosomes were efficiently taken up by lung cancer cells, which led to effective knockdown of the SOX2 gene and decreased the stem cell population of lung cancer cells (CD44+/CD24− cells)." (PMID 39355533, 2024). "The bioinformatics-based association analysis identified candidate exosomal proteins associated with lung cancer, including SPP1, CD44, ALB, SPARC, CAT, GAPDH, and CADM1." (PMID 39766023, 2024). "Human CD44 straining was further used to prove that the human lung cancer cells migrated into lung tissues of mice." (PMID 38383737, 2024). "The top candidate exosomal proteins associated with lung cancer, based on the number of publications supporting the association, included SPP1, CD44, ALB, SPARC, CAT, GAPDH, and CADM1." (PMID 39766023, 2024). "Our recent LUAD study showed that CD44+ lung cancer stem cells promoted brain metastases via GPR124-enhanced trans-endothelial migration." (PMID 39080406, 2024).
lung carcinoma (continued). "Earlier, we published that IGFBP-3 binds HA through residues 215–232 in the C-terminal region of the protein and blocks HA interactions with its receptor, CD44, reducing viability of A549 human lung cancer cells." (PMID 36766747, 2023). "Abundant evidence confirms that CD44 functions as a CSC surface marker in lung cancer and regulates several important properties related to cancer stemness, including self-renewal, tumor initiation, and metastasis." (PMID 37726816, 2023). "Both analyses showed that the H1299 cell line expressed higher levels of CD44 compared with the other lung cancer cell lines." (PMID 37399498, 2023). "For this purpose, we chose several common markers associated with lung cancer CSCs: aldehyde dehydrogenase (ALDH), CD44, Octamer-binding transcription factor 4 (Oct4), KIT proto-oncogene, receptor tyrosine kinase (c-Kit), and Nestin." (PMID 37233697, 2023). "The expression of CD44 is higher in multiple tumor cells than that in corresponding normal tissues, such as lung cancer." (PMID 37507782, 2023). "BACH1 can activate CD44, and MAPK signalling in lung cancer stem cells (CSCs) and stimulate lung cancer metastasis; its loss represses metastasis in xenograft models." (PMID 37963558, 2023). "In lung cancer, CD44 downregulation was involved in sensitization to cisplatin and gefitinib, whereas lower CD44 expression in tumors was associated with better recurrence-free survival." (PMID 38067149, 2023). "Another cytokine secreted by M2 macrophages, TGF-β1, induces EMT in primary lung cancer cells through the downregulation of miR-138 with a subsequent increase in the colony-forming ability and expression of stem cell markers CD44 and CD90 in lung cancer cells." (PMID 38139154, 2023). "We confirmed that CD44 and ITGB1 are PI4K2A-associated proteins and that SPP1 binds to CD44 and ITGB1 in mesenchymal lung cancer cells." (PMID 36757799, 2023). "The major stem cell markers for lung cancer include surface biomarkers, such as CD44, CD133, and integrin α6, and intracellular biomarkers, such as ALDH1, Nanog, Oct4, and Sox2." (PMID 37298389, 2023). "A study showed that CD44 facilitated CD133+CD44+ lung cancer stem cells metastasis via Wnt/β-catenin-FoxM1-Twist signaling." (PMID 36895477, 2023). "As per the existing literature, CD44 functions as the marker initiating tumors in lung cancer cells, as demonstrated in both in vitro and in vivo tests." (PMID 38132948, 2023). "Cells were treated with MβCD, Simva, or SMase to determine the effect of cholesterol depletion on CD44 surface expression of lung cancer cells by flow cytometry." (PMID 37399498, 2023). "Primary lung tumors with highly expressed CD44 demonstrated increased metastasis to the regional lymph nodes, and CD44 enhanced the ability of lung cancer cells to migrate and invade." (PMID 38067149, 2023). "In this regard, an important achievement in lung cancer has recently been reached through the study of CD44+/EPCAM+ cell populations, which showed a high correlation and affinity with CSCs, previously identified by ALDH high cells." (PMID 35205721, 2022). "CD44 is an adhesion glycoprotein that plays important roles in breast, colorectal, thyroid and lung cancer progression and metastasis." (PMID 35853934, 2022). "Investigation of the molecular mechanism showed that E2 increases RNF4 expression to reduce Sp1 levels, thereby enhancing CD44 expression through downregulation of several miRNAs, and this leads to a poor prognosis in young women with lung cancer." (PMID 35034634, 2022). "Sp1 inhibited CD44 expression by increasing the expression of miR-3194-5p, miR-218-5p, miR-193-5p, miR-182-5p and miR-135-5p, ultimately resulting in lung cancer malignancy." (PMID 35034634, 2022).